MYCNUT (MYCN upstream transcript)
Synonyms: lncUSMycN; MYCNUN
Gene: Long non-coding RNA gene on chromosome 2 (15,908,664 to 15,937,784, forward strand). Ensembl gene ENSG00000223850.
Diseases named in the same sentence as MYCNUT in open-access papers:
MYCNUT is named in the same sentence as 2 diseases in open-access papers, as found by Europe PMC text mining. Sharing a sentence is not in itself a finding about the gene and the disease.
MYCNUT shares sentences with these, for which no sentence is quoted: cancer (2 papers); breast carcinoma (1).